EGFR (epidermal growth factor receptor)
Diseases named in the same sentence as EGFR in open-access papers (continued):
Sharing a sentence is not in itself a finding about the gene and the disease.
tumor (continued). "The new series of sulfa azo 4H-chromene esters (7a–g, 8, and 11a–e) were adapted and assessed for their inhibitory behavior against the HCT-116, MCF-7, and HepG-2 tumor cell lines, targeting EGFR, MMP-2, and Carbonic anhydrase CAII." (PMID 38069037, 2023). "Epidermal growth factor receptor (EGFR) belongs to the receptor tyrosine kinase family (ErbB) that regulates tumor cell differentiation, survival, and proliferation." (PMID 38327269, 2023). "In detail, the authors noticed the co-amplification of SMO and MET genes in tumour samples taken as the clinical evidence of EGFR-TKI resistance in 2 of the 16 patients." (PMID 37376053, 2023). "Confocal microscopy confirmed the peptide binding specificity to EGFR-positive MDA-MB-231 tumor xenograft tissues and their co-localization with the membrane EGFR." (PMID 37048151, 2023). "Generally speaking, the majority of tumor recurrences in patients treated with an EGFR-TKI occur at the primary site." (PMID 37046679, 2023). "Among the EGFR-amplified tumours, of 18,609 transcripts after filtering poorly expressed species, 21 transcripts were differentially expressed (padj < 0.05)." (PMID 36765632, 2023). "HIF-2α mainly induces angiogenic factors, such as VEGF, VEGFR, EGFR etc., promoting angiogenesis and tumor growth." (PMID 36865554, 2023). "It is nowadays well established that abnormal expression of EGFR can regulate tumor cell proliferation, migration, differentiation, and homeostasis, and even in GBM, more than half of patients have genetic variants of EGFR." (PMID 36480032, 2023). "These molecular recurrences, detected in the cfDNA, are a complement to tumor tissue biopsy analysis and can identify alterations of resistance, such as EGFR p.T790M and EGFR p.C797S." (PMID 36900363, 2023). "Knockdown of GSDMD suppressed tumor proliferation by promoting the mitochondrial apoptotic pathway and inhibiting the EGFR/Akt signaling pathway in NSCLC." (PMID 37371484, 2023). "Together, our findings highlight the importance of adaptive immune activation in the anti-tumor activity of EGFR-TKIs." (PMID 36817465, 2023). "Our previous investigations underscored that the anti-tumor efficacy of ALDOA is facilitated by its interaction with EGFR." (PMID 37896207, 2023). "The most common reason for discontinuing EGFR-TKI therapy is tumor progression, and therefore, personalized prediction of EGFR-TKI resistance is notable." (PMID 36670497, 2023). "The surface of modified EVs was enriched in GPI-bound anti-EGFR nanobodies compared to parental cells, which significantly improved the binding of EVs to EGFR-expressing tumor cells." (PMID 37686050, 2023). "In the present study, mechanisms of aggressiveness of BLBC involving EGFR and/or HER2 expression and interactions between tumor and tumor-associated macrophages (TAMs) were explored." (PMID 36674955, 2023). "Quercetin has been shown to inhibit proliferation in several cancer cell lines, and one study found that quercetin had anti-tumor activity in NSCLCs harboring wild-type EGFR by inhibiting AXL and inducing apoptosis." (PMID 36959600, 2023). "The drug effectively inhibited the growth of tumor cell lines of epidermal, pancreatic, and colorectal origins with EGFR overexpression in vitro." (PMID 38201251, 2023). "The tumor reduction rates in the EGFR CAR-T and EGFR CAR-E27-T groups were 40% and 80%, respectively, and those in the EGFR CAR-E27-CCR6-T group were almost completely eliminated." (PMID 36982500, 2023).
tumor (continued). "Collectively, we assume that inhibition of the EGFR-HIF1a signaling pathway by EGFR-TKI administration suppressed the expression of HIF1a in the tumor, resulting in lower angiogenetic activity and leading to the lack of PTBE on imaging." (PMID 37719531, 2023). "ATM inhibitors radiosensitized NSCLC by inhibiting IR-induced EGFR activation and can be used in EGFR-resistant tumor cells for radiotherapy." (PMID 36865554, 2023). "Key research avenues encompassed the tumor microenvironment, epidermal growth factor receptor, clinical trials, and interleukin pathways." (PMID 38259287, 2023). "The prophylactic and therapeutic anticancer effects of the EGFR L2 vaccine were evaluated in a mouse tumor model." (PMID 36851313, 2023). "Each of the next generations of EGFR-targeting drugs was designed to overcome drug resistance of tumor to the previous generation or to reach those patients for whom the previous generation did not initially work." (PMID 38201251, 2023). "These in vitro and in vivo data from cell lines, acquired resistant clones, and patient-derived cells indicated that 35d have potential to inhibit tumor growth in EGFR-mutant LUADs with distinguished TKI-resistance mechanisms, including EGFR C797S mutation." (PMID 37178919, 2023). "Comparable to the two-in-one antibody HCP-LCE, it exhibits specific cellular binding on EGFR and PD-L1 double positive tumor cells, blocks the PD-1/PD-L1 axis and mediates a potent ADCC effect as an NKCE." (PMID 37081888, 2023). "Targeting EGFR is attractive for cancer therapy due to its involvement in tumor initiation, angiogenesis, and metastasis." (PMID 38057816, 2023). "For patients with RAS/BRAF wild-type tumours, the use of an anti-EGFR agent with FOLFOX or FOLFIRI is an accepted policy in left-side primary tumours with CRCLM." (PMID 36674640, 2023). "IL-8 has been shown to be involved in inflammatory microenvironment and tumor cell proliferation through activation of EGFR." (PMID 37868614, 2023). "In vivo, Gefitinib and other EGFR-TKI drugs widely inhibit the tumor growth of human tumor cell derived lines xenografted in nude mice, and improve the anti-tumor activity of chemotherapy, radiotherapy and hormone therapy." (PMID 36959566, 2023). "This work demonstrated how the cross-linking of EGFR-expressing breast cancer cells and T-cells effectively promoted anti-tumor immunity." (PMID 37345176, 2023). "EGFR/Notch bispecific antibodies decrease the subpopulation of stem-like cells, reduce the frequency of tumour-initiating cells, and downregulate mesenchymal gene expression." (PMID 37441599, 2023). "In HNSCC, upregulation of FAS and its regulator, epidermal growth factor receptor (EGFR), is positively associated with HPV-negative tumor progression and metastasis." (PMID 37370794, 2023). "Further studies have confirmed that the EGFR/PI3K signaling pathway plays an important role in tumor chemoresistance." (PMID 38026933, 2023). "Triazole-substituted quinazoline derivatives have been synthesized for their epidermal growth factor receptor (EGFR) tyrosine kinase activity and demonstrated moderate activity in tumor cell lines (HCT116, MCF-7 and PC-3)." (PMID 37111343, 2023). "Previous studies have shown that the activation of EGFR signaling pathway is significantly related to the proliferation and invasion of various parenchymal tumor cells." (PMID 37662915, 2023). "Autocrine stimulation of EGFR by AREG and EREG is a mechanism of tumor EGFR pathway dependence, so the impact of their expression on the response to EFGR-targeted therapy in mCRC patients has also received much attention." (PMID 37974093, 2023). "The overexpressed epidermal growth factor receptor (EGFR) gene participates in a variety of tumor progression and development pathways." (PMID 37668041, 2023).
tumor (continued). "Given that the EGFR/PI3K/AKT/mTOR signaling pathway exerts strong tumor-promoting effects on HCC, it is reasonable to attempt to inhibit this pathway for the treatment of HCC." (PMID 37631344, 2023). "This drug specifically recognizes and binds to EGFR on the surface of tumor cells, subsequently activating the Hippo pathway through tyrosine phosphorylation." (PMID 37305567, 2023). "Compared to the adjuvant control group, Emut Vax decreased tumor load by ~70% for both EGFR mutant tumor cell lines, indicating a strong protective effect." (PMID 36875137, 2023). "A significant PFS [7.2 vs 3.6 months, HR 0.43 (95% CI 0.2-0.76), p= 0.004] and OS benefit [14.9 vs 10.9 months, HR 0.52 (95% CI 0.28-0.98), p= 0.045] in favor of anti-EGFR therapy vs R/T was observed in the L-sided tumor group." (PMID 36895480, 2023). "TGF-α exerts its effect on cell proliferation by stimulating EGFR dependent cell signaling leading to ccRCC tumor growth." (PMID 36831657, 2023). "Several ongoing and published clinical trials are currently evaluating IRDye800‐labeled antibodies targeting alternative biomarkers (VEGFR or EGFR) to distinguish tumor lesions." (PMID 37476052, 2023). "Our qRT-PCR analysis showed that MUC1 expression levels in the tumour tissues were 1.7-fold higher than that in the tumour-far normal tissues (p < 0.0001), consistent with upregulation of EGFR gene expression in the same tumour tissues (p < 0.0001)." (PMID 36810913, 2023). "Cetuximab binding to EGFR has been seen to disrupt ligand binding and consequently lead to apoptosis of tumor cells." (PMID 39086690, 2023). "The tumor volume shrunk by about 63.7% for anti-EGFR-iRGD VHHs, outcompeting the anti-EGFR VHHs group." (PMID 37746282, 2023). "The results showed that transcriptional activation of the cell cycle pathway positively correlated with increased tumor-tumor interactions and, by extension, improved survival benefit from EGFR TKI treatment." (PMID 36647832, 2023). "Two anti-EGFR LiTEs, produced in two orientations, i.e., as EGFR(Nb)/CD3(scFv) and CD3(scFv)/EGFR(Nb), showed enhanced T-cell activation and significant inhibition of EGFR-expressing tumor cells." (PMID 36761751, 2023). "EGFR activation was closely correlated with tumor proliferation, invasion, metastasis and chemoresistance." (PMID 36639822, 2023). "The EGFR antibody allows specific targeting of the NPs inside the tumour cells followed by conversion of the prodrug 5-fluorocytosine (5-FC) to the anticancer drug 5-FU by the enzyme CyD." (PMID 38112935, 2023). "A significant increase was observed in single-nucleotide variants in the genes ATM, ATR, BRCA1, LRP1B, MAP2K1, PIK3CG and ZNF217 in addition to BRAF, KRAS, NRAS and EGFR among tumours receiving prior anti-EGFR." (PMID 37569598, 2023). "The mo-Macs were predicted to deliver activation signals through the TNFR (TNF-TNFRSF1A), TGFBR (TGFB1-TGFBR2), and EGFR (EREG-EGFR) pathways to tumor cells." (PMID 37187731, 2023). "In this study, we characterized tumor genomic landscapes in 142 patients with EGFR 20ins-postive NSCLC." (PMID 37308490, 2023). "A markedly suppressed effect on the EGFR/ERK/NF‐κB pathway was found in mice tumour tissue treated with both 18β‐GA and RT as compared to monotherapy." (PMID 37177859, 2023). "In the neuroblastoma, EGFRvIII is a highly specific tumor neoantigen, whereas EGFR is a TAA that is highly expressed in both tumor cells and many normal tissues." (PMID 37596653, 2023). "Previous research also demonstrated the role of the EGFR and its downstream signaling pathways in sustaining tumor development and homeostasis." (PMID 37685910, 2023). "Activation of EGF/EGFR signaling pathway promoted tumor progression and enhanced the malignant potential of OSCC cells through cellular uptake of TEXs." (PMID 36768288, 2023).
tumor (continued). "Our analysis showed a significant longer PFS and OS for patients treated with anti-EGFR vs R/T in the L-sided tumor group [median PFS 7.2 vs 3.6 months, HR 0.43 (95% CI 0.2-0.76), p=0.004; median OS 14.9 vs 10.9 months, HR 0.52 (95% CI 0.28-0.98), p=0.045]." (PMID 36895480, 2023). "Analysis of tumor RNA-seq data showed that T cell inflamed signature was significantly enriched upon EGFR-TKI treatment in patients with prolonged response (TTP > 12 months) but not in patients with short duration of response (TTP of 0 – 8.6 month)." (PMID 36817465, 2023). "A number of studies investigated the diagnostic accuracy of ctDNA in patients who progressed after anti-EGFR TKIs, and showed a very wide range of concordance with tumour tissue analyses." (PMID 37047382, 2023). "For example, the anti-EGFR nanobody can inhibit tumor cell proliferation by inhibiting the intracellular tyrosine kinase signaling pathway network." (PMID 36835588, 2023). "ATO significantly diminished the number of clusters of tumor cells derived from the pleural effusions of NSCLC patients who harbored all kinds of EGFR genotypes (p < 0.001, p < 0.01, p < 0.05)." (PMID 37371816, 2023). "In this review, we turn to data on the epidermal growth factor receptor (EGFR), which is one of the main tumor markers in many types of cancer." (PMID 37754201, 2023). "One quarter of the tumors were found to express epidermal growth factor receptor (EGFR), with the majority of those being PB (n = 10/24) and only one tumor being INT (p = 0 = 002)." (PMID 38136318, 2023). "It seems that the overexpression of EGFR in OCCs depends on the tumor stage, invasion, metastasis to the lymph nodes, distant metastasis, and differentiation of cancer." (PMID 39144672, 2023). "Increased VEGF levels, which have been confirmed in cancers with acquired resistance, lead to the preservation of tumor growth when the tumor is under attack from EGFR TKIs." (PMID 36865093, 2023). "For instance, the expression of miR-125a-5p, which exerts its antitumor effects by targeting EGFR, is decreased in human tumor cells." (PMID 37371458, 2023). "Tumor xenograft models were used to test the in vivo antitumor activity of panobinostat alone or its combinations with gefitinib, an EGFR-tyrosine kinase inhibitor (TKI)." (PMID 37537339, 2023). "To show the full potential of CONNECTOR in a complex use case, we analyzed a large dataset of tumor growth curves of PDXs from mice treated with cetuximab, an anti-EGFR antibody that is approved for clinical use in patients with RAS/RAF wild-type mCRC." (PMID 37079732, 2023). "Cell proliferation, colony formation, wound healing, migration assays, tube formation assays, and tumor growth assays were used to study the function of miR-218-5p/EGFR signaling." (PMID 36831545, 2023). "To examine the spatial and molecular heterogeneity at the EGFR locus, we selected one treatment-naive tumor (P129) with the highest number of multi-regional biopsies from CE and NE regions for focused analysis." (PMID 37770427, 2023). "If the tumor is left-sided, RAS, or BRAF wild-type, you should check that the patient did receive prior anti-EGFR therapy and that patients with dMMR or BRAF V600E mutated tumors have been exposed to immunotherapy and BRAF inhibitors, respectively." (PMID 38201553, 2023). "Patients with the highest intra-tumor ERBB1 mRNA expression levels (top 40%, EGFR/ERBB1high) had worse DFS and OS than patients with the lowest intra-tumor ERBB1 mRNA levels (bottom 40%, EGFR/ERBB1low)." (PMID 37240940, 2023). "Bags predicted to be EGFR mutant also had higher minimum tumor nuclei fraction (p = 0.037, Pearson’s r: 0.301) and lower maximum peritumoral immune fraction (p = 0.041, Pearson’s r: − 0.297)." (PMID 36927889, 2023). "We demonstrated that topographical cues stimulated phenotypic changes in bulk tumor cells, including enhanced EGFR activity and enrichment of CSCs, supporting their potential for cell-based assays." (PMID 36968199, 2023).
tumor (continued). "Western blot analysis showed that SLURP-1 extracted both α7-nAChR and EGFR from the tumor homogenate, while Oncotag bound only α7-nAChR." (PMID 37854069, 2023). "The results demonstrate that miR-218-5p acts as a tumor suppressor via targeting EGFR in As-T cells-induced tumor growth and angiogenesis in vivo." (PMID 36831545, 2023). "Engineered exosomes target tumor cells through specific binding of GE11 or EGF to EGFR on the surface of cancer cells." (PMID 36839784, 2023). "Treatment of tumor cells with neuraminidases or a sialyl transferase inhibitor significantly reduced binding of a soluble recombinant Siglec-9-Fc fusion protein, while EGFR and HER2 expression remained unchanged." (PMID 37346044, 2023). "EGFR is a direct target gene of Wnt signaling, and aberrant Wnt signaling is known to be involved in neoplasia and drug resistance in multiple types of cancer." (PMID 36869126, 2023). "In other studies, a high baseline T790M load and high baseline EGFR VAF are associated with poorer outcomes, potentially due to increased tumour load." (PMID 37894366, 2023). "The upstream signaling pathway, the epidermal growth factor receptor (EGFR) signaling pathway, participates in the control of tumor cell proliferation, inhibits cell apoptosis, and promotes cell cycle progression." (PMID 36994237, 2023). "EGFR drives metastasis in many ways, including paracrine loops comprising tumor and stromal cells that enable EGFR to fuel invasion across tissue barriers, survival of clusters of circulating tumor cells, and colonization of distant organs." (PMID 37242487, 2023). "Primary resistance, or early tumor progression, is a common phenomenon where 20–30% of patients are insensitive to EGFR-TKIs from the beginning, despite the more prevalent acquired resistance to tumor-targeted therapies." (PMID 36835536, 2023). "Gefitinib, an EGFR inhibitor, significantly suppressed C4-2 cell proliferation and growth of a xenografted C4-2 tumor in castrated mouse." (PMID 37463954, 2023). "Both in vitro and in vivo studies on EGFR mutant osimertinib-resistant NSCLC models demonstrated that BBP-398, alone or in combination with osimertinib, an EGFR inhibitor, exhibited a potent tumor-suppressing activity." (PMID 38001644, 2023). "BND-22 improved the therapeutic efficacy of anti-EGFR or anti-PD-1 antibodies in murine tumor models." (PMID 37781391, 2023). "Several other OVs armed with BiTE, such as FAP and EGFR, have proved to enhance T-cell activation and accumulation in the tumor site, resulting in higher anti-tumor efficacy." (PMID 37631987, 2023). "In the present paper, we compare some aspects of EGFR functioning in enMSC as an example of normal cells and in tumor-derived HeLa cells." (PMID 37686213, 2023). "The suppression of tumor growth upon loss of hepsin was accompanied by downregulation of TGFβ and EGFR signaling together with a reduction in epidermal growth factor receptor (EGFR) protein levels." (PMID 37872868, 2023). "Overexpression and/or overactivation of the Epidermal Growth Factor Receptor (EGFR) is oncogenic in several tumor types yet targeting the kinase domain of wildtype EGFR has had limited success." (PMID 36253541, 2023). "Clearly, low affinity to endogenous EGFR and enhanced binding to tumor-specific EGFRvIII binding is necessary for the high efficacy of CARs." (PMID 36721153, 2023). "In patients with EGFR‐mutated stage IB‐IIIA NSCLC, adjuvant osimertinib after full tumor excision dramatically increases DFS and reduces the risk of both local and distant recurrence." (PMID 38077251, 2023).